USP7 (ubiquitin specific peptidase 7)
Diseases named in the same sentence as USP7 in open-access papers (continued):
Sharing a sentence is not in itself a finding about the gene and the disease.
tumor (continued). "In conclusion, USP7 deubiquitinated MTDH to stabilize its expression, and then contributed to CC cell proliferation, migration, invasion, and angiogenesis, as well as macrophage M2 polarization in vitro, and enhanced tumor growth in nude mice." (PMID 38625581, 2024). "Studies have shown that cisplatin and paclitaxel activate the USP7/hnRNPA1 axis to promote CAF secretion of miR-522, which inhibits the activity of ALOX15 in tumor cells, reduces ROS production, and inhibits ferroptosis in tumor cells." (PMID 39769177, 2024). "This indicates that patients with a USP7 high-expressing tumor do not benefit more from radiotherapy than patients with USP7 low-expressing tumors under standard therapy." (PMID 38672118, 2024). "Interestingly, USP7 and USP13 had similar mock and ZIKV-treated tumor/non-tumor cell proportions at 7 dpi." (PMID 39599878, 2024). "USP7 modulates in vivo TME by decreasing VEGF, tumour vasculature and growth." (PMID 38602256, 2024). "Convincingly, we verified the negative correlation between the protein levels of USP7 and DICER by using data from the clinical proteomic tumour analysis consortium (CPTAC), which was consistent with our experimental results that USP7 negatively regulated the DICER protein level." (PMID 37867415, 2024). "Furthermore, both USP7 and MDM2 mRNAs were highly expressed in tumour tissues, but DICER mRNA was highly expressed in normal tissues." (PMID 37867415, 2024). "Functionally, USP7 inhibition in the CT‐26 syngeneic mouse model led to increased recruitment of CD8+ lymphocytes to the tumour but did not affect CD4+ or regulatory T‐cells." (PMID 38602256, 2024). "The oral USP7 inhibitor, ADC‐159, reduces sVEGF from CAFs and impacts tumor vasculature." (PMID 38602256, 2024). "Our previous data using CRC cell lines and organoids showed that USP7 is essential for pathological WNT activation in APC mutant cells but not physiological WNT signaling in normal cells, suggesting that USP7 can be used as tumor-specific drug target." (PMID 36669491, 2023). "In contrast, when USP7 was knocked out, NSCLC tumour growth was strikingly decreased." (PMID 38082439, 2023). "Furthermore, abrogated USP7 expression inhibits the M2 macrophages transformation and their function, and promotes IFN-γ+CD8+ T cells infiltration, augmenting anti-tumor immunity." (PMID 37415977, 2023). "The levels of USP7, EZH2, and FOXO1 were found to be correlated with tumor histological grades." (PMID 35884430, 2022). "Importantly, overexpression of USP7 correlated with TAZ upregulation, tumor aggressiveness and unfavorable prognosis in HNSCC patients." (PMID 35931679, 2022). "This situation is not unique to USP7 but applies broadly to genes that exhibit properties of haploinsufficient tumor suppressors." (PMID 33664368, 2021). "In AML, Cartel and colleagues reported that the early USP7 inhibitor P22077 reduces viability of primary AML cells in vitro and tumor burden in vivo in PDX (patient-derived xenograft) models, and suggested USP7-mediated stabilization of CHK1 as one mechanism contributing to cytotoxicity." (PMID 34359655, 2021). "To validate this hypothesis, we first analyzed the protein levels of USP7, EZH2 and FOXO1 in human tissue arrays, including a series of paired tumor and adjacent normal tissue samples from the breast, kidney, lung, lymph node, ovary, esophagus and skin." (PMID 33849069, 2021). "Similarly, the treatment of USP7 inhibitors (P5091 or P22077) also suppressed the activation of NF-κB, and a combination of USP7 inhibitors and BTZ triggered the synergistic anti-tumor activity in BTZ-resistant MM cells." (PMID 33967786, 2021).
tumor (continued). "Interestingly, in human breast tumor samples, USP7 and PHF8 protein levels correlate with tumor grade." (PMID 34577547, 2021). "We showed that the expression of both USP7 and EZH2 elevates during tumor progression, corresponding to a diminished FOXO1 expression, and the level of the expression of USP7 and EZH2 strongly correlates with histological grades and prognosis of tumor patients." (PMID 33849069, 2021). "Interestingly, USP7 also promotes TNF-induced apoptosis through its combination with TRIM27 and receptor-interacting protein 1 (RIP1), indicating the tumor-suppressive role of USP7." (PMID 34869041, 2021). "Besides controlling AR and ARv7, USP7 is also in charge of the stability of the CCDC6 gene product, a tumor suppressor whose impairment induces a BRCAness-like phenotype which associates to PARP inhibitors sensitivity in prostate and urothelial cancer." (PMID 33546726, 2021). "Preclinical studies have shown that USP7 small-molecule inhibitors such as P22077, P5091, GNE-6640, GNE-6776, and HBX19818 are well tolerated, induce efficient tumor-cell cytotoxicity, and selectively inhibit target molecules in in vitro and in vivo conditions." (PMID 32354135, 2020). "Moreover, the DUB USP7, USP13, USP22, USP28, USP36 and USP37 stabilize c-Myc, thereby stimulating tumor growth." (PMID 33004065, 2020). "Targeting USP7 with P5091 up-regulated the expression of PD-L1 in TME, indicating that the combination with PD-1 monoclonal antibody therapy may improve the anti-tumor effect of the treatment." (PMID 32802195, 2020). "In order to test the significance of combined tissue IHC-expression of CCDC6 and USP7 we performed a non-parametric Spearman correlation test that proved to be extremely significant across all the tumor samples." (PMID 30786932, 2019). "By this approach, then, we could further stratify the G3 tumor category into two different groups based on the expression pattern of CCDC6 and USP7." (PMID 30786932, 2019). "Compared with the non-specific shRNA (NC) transfected cells, knockdown of USP7 (shUSP7) significantly inhibited tumor growth in nude mice." (PMID 27780924, 2016). "Moreover, CETSA assays showed that CDDO-Me treatment increase the thermal stability of USP7 in tumor tissues, indicating the interaction of CDDO-Me and USP7." (PMID 27780924, 2016). "USP7 upregulation was detected in 57 out of 110 (51.82 %) tumor tissues compared with their adjacent non-tumorous tissues." (PMID 25519684, 2015). "In vivo, in a xenograft mouse model, DHPO treatment significantly reduced tumor volume without observable signs of systemic toxicity, suggesting that USP7 functions as a ferroptosis regulator and may represent a promising therapeutic target." (PMID 40861444, 2025).
tumor (continued). "Furthermore, while the experimental results revealed the functional significance of the interactions between DACH1 and USP7, the universality of these interactions in clinical samples and their role in tumor heterogeneity have not been thoroughly explored." (PMID 40389405, 2025). "Interestingly, viral particle accumulation was augmented even in the cell line that showed no reduction in tumor cell proportion over time (USP7), indicating a high replication rate not necessarily accompanied by oncolytic effect in ATRT cells in vitro." (PMID 39599878, 2024). "Considering the results in the context of the in silico analysis, it can be assumed that USP7 overexpression does not contribute to improved DNA repair but to chromosomal instability of the tumor by deregulating DNA replication and repair, which in turn contributes to the poor prognosis." (PMID 38672118, 2024). "Notably, USP7, ATXN3, CSN5, and USP51 participate in tumor immunity within the GC microenvironment." (PMID 39605891, 2024). "Besides, dysregulation in post-transcriptional modifications, like ubiquitination enzymes (HUWE1, CUL4A, TRIM25, etc.)and deubiquitination enzymes (USP7, USP10, USP24, etc.)in these PTC tumor samples may also lead to the low consistency." (PMID 38609408, 2024). "Notably, we found that USP7 inhibition increased gene expression levels of ICAM‐1 (log2 fold changes = .85, padj = .017), VCAM‐1 (log2 fold changes = .72, padj = 1.9 × 10−4), and ITGB‐2 (log2 fold changes = 1.26, padj = 1.84 × 10−4) in the tumour." (PMID 38602256, 2024). "We further demonstrate that de-ubiquitinating enzyme USP7 interacts with SAMHD1 and de-ubiquitinates it at lysine 421, thus stabilizing SAMHD1 protein expression for further interaction with CtIP for DDR, which promotes tumor cell survival under genotoxic stress." (PMID 37081042, 2023). "At the same time, the expression of USP7 was negatively correlated with molecules related to negative immune regulation, such as PD-L1, Tim3, and TGF-β, indicating that USP7 may negatively regulate the expression of PD-L1 in tumor cells." (PMID 32802195, 2020). "Unlike MDM2 inhibitors, USP7 inhibitors were well tolerated in mice at doses that effectively inhibited tumor growth, suggesting that pharmacological inhibition of USP7 may be safer than inhibition of MDM2." (PMID 32064756, 2020). "However, the mechanism of PD-L1 expression up-regulation by targeting USP7 in Lewis tumor cells is not clear and we plan to further explore it in the future." (PMID 32802195, 2020). "We generated three gastric fibroblast cell strains with the knockdown of USP7, hnRNPA1 and miR-522 respectively by using lenti-viruses containing shRNAs, and these fibroblast cell strains were mixed with SGC7901 cells for subcutaneous tumor implantation in mice." (PMID 32106859, 2020).
tumor (continued). "Finally, miR‐367 silencing also significantly inhibited 3D cell invasion in tumor spheroids of both USP13‐MED and USP7‐ATRT cells, suggesting that miR‐367 silencing inhibits two key features of tumor aggressiveness, namely, stem‐like properties and invasive behavior." (PMID 31402560, 2019). "Importantly, USP7 inhibition does not affect normal cells with WT APC, indicating that USP7 can be used as a tumor-specific drug target for APC-mutated CRCs." (PMID 29045831, 2017). "Independent of the tumor dispersion pattern into the brain organoids, these data show the capability of the LN18, U343-MG, USP7 and USP13 cells to adhere and grow in this organoid model." (PMID 39599878, 2024). "The qRT‐PCR results verified that PX‐478 had no impact on the mRNA levels of USP7 or NRF2 in THP‐1 cells, as was the case with shcirc‐1000519 transfection in tumour cells." (PMID 39107958, 2024). "Moreover, this study discovered a previously unreported mechanism in which USP7 enhances the oncogenic activity of DACH1 by stabilizing it, a function not previously documented in tumor research." (PMID 40389405, 2025).
infection (25 papers, 2013 to 2025). The state of being infected such as from the introduction of a foreign agent such as serum, vaccine, antigenic substance or organism. "Altogether, these data clearly show that the UBM2 mutation in DBP is neglectable for efficient recruitment of USP7 into RCs during late time points of a productive HAdV-C5 infection." (PMID 35254132, 2022). "As expected, USP7-inactivated mice were more susceptible to infection with Salmonella typhimurium." (PMID 36032091, 2022). "Furthermore, we observed USP7-deficient mice to be more susceptible to infection by Salmonella typhimurium." (PMID 36032091, 2022). "So we speculate that USP7 may be an attractive target for controlling infection and other malignancies caused by these viruses." (PMID 31114498, 2019). "Infection with Usp7-overexpressing adenovirus markedly elevated PPARγ levels in hepatocytes and increased Usp7 expression." (PMID 36834633, 2023). "We show that DBP expression and stability and viral DNA replication in UBM2 H5pm4250 infections are widely comparable to WT H5pg4100 despite the affected recruitment of USP7 into RCs at the 24-hpi time point." (PMID 35254132, 2022). "In contrast, at 24 h and 48 h after infection with WT H5pg4100, the intensity of diffuse nuclear staining was greatly reduced, and in all of the infected cells examined (n > 140), USP7 was clearly seen concentrated in DBP-positive RCs." (PMID 35254132, 2022). "While flag-E4orf6/DBP was recruited to USP7-marked VRCs during infection, flag-E4orf6 remained markedly diffuse throughout the nucleus." (PMID 36095031, 2022). "Previously, we identified that the cellular ubiquitin-specific protease 7 (USP7), a deubiquitinating enzyme, localizes in viral RCs after HAdV-C5 infection." (PMID 35254132, 2022). "Combined immunoprecipitation/immunoblotting experiments show that DBP specifically interacts with USP7 in WT H5pg4100-infected H1299 cells upon USP7 overexpression or with endogenous USP7 in infection experiments of HCT116 cells." (PMID 35254132, 2022). "Since the USP7-mediated deubiquitination of MyD88 results in greater stability of MyD88 protein, and an uncontrolled innate immune response always results in greater susceptibility to infection, we speculated that P5091-treated mice would also exhibit less severe inflammatory responses." (PMID 36032091, 2022). "Our data indicate that in the context of infection also, vIRF-2 competes for USP7 interactions with TRAFs 3 and 6 and consequently promotes their polyubiquitination and associated signal transduction." (PMID 31666375, 2020). "USP7 appears to bind and stabilize ICP0, but ICP0 degrades USP7 late during infection in a RING finger-dependent manner." (PMID 33374862, 2020). "To keep USP7 levels low, potentially avoiding artifacts of overexpression, we delivered FLAG-USP7 in an adenovirus expression system at low multiplicity of infection that resulted in expression in ~70% of the cells at levels close to endogenous." (PMID 30804394, 2019). "Using high MOI, cells started to form small USP7 clusters in the nucleoplasm at ∼9 to 15 hpi, showing that the onset of replication occurs in a narrow time window after initial infection." (PMID 29997215, 2018). "As expected, the observed inefficient synthesis of the early viral proteins resulted in delayed accumulation of late structural proteins in both APU6 and HU5 cells compared to the USP7+ counterparts during wt infection (H5pg4100)." (PMID 23555268, 2013). "We demonstrate that USP7 ensures stability and/or proper expression levels of adenoviral proteins at early and late time points of infection." (PMID 23555268, 2013). "Moreover, infection of Usp7-expressing adenovirus increased PPARγ levels in the liver of mice and accelerated the development of fatty liver." (PMID 36834633, 2023).